MAGEH1 (MAGE family member H1)
Synonyms: APR-1; APR1; MAGEH
Tractability: PROTAC: ubiquitination databases record sites on it.
Gene: Protein-coding gene on chromosome X (55,452,127 to 55,453,566, forward strand). Ensembl gene ENSG00000187601.
Subcellular location (Human Protein Atlas): Nucleoli; Nucleoli rim
Gene Ontology:
Molecular function: protein binding
Biological process: apoptotic process; negative regulation of transcription by RNA polymerase II
Cellular component: nucleolus; nucleus
Homologues: Orthologues: chimpanzee MAGEH1 (100% identical), macaque MAGEH1 (100% identical), pig MAGEH1 (96% identical), rabbit MAGEH1 (94% identical), mouse Mageh1 (93% identical), rat Mageh1 (92% identical), zebrafish ndnl2 (28% identical), Drosophila melanogaster MAGE (16% identical). Paralogues in human: MAGED1 (35% identical), MAGED2 (34% identical), TRO (34% identical), MAGED4 (33% identical), MAGED4B (33% identical), MAGEL2 (33% identical), MAGEE1 (32% identical), NSMCE3 (32% identical), MAGEF1 (32% identical), MAGEB6B (30% identical), NDN (30% identical), MAGEB17 (29% identical), and 25 more.
Diseases named in the same sentence as MAGEH1 in open-access papers:
MAGEH1 is named in the same sentence as 26 diseases in open-access papers, as found by Europe PMC text mining. Sharing a sentence is not in itself a finding about the gene and the disease. The quoted sentences say what the papers report.
breast carcinoma (3 papers, 2019 to 2022). "MiR-874, miR-143-3p, miR-876-5 and miR-6775-3p have also been shown to contribute to the down-regulation of MAGE gene expression in cancer cells and vice versa, MAGEH1 can suppress breast cancer metastases through upregulating mir-200a/b expression." (PMID 31143371, 2019).
melanoma (3 papers, 2019 to 2025). A malignant, usually aggressive tumor composed of atypical, neoplastic melanocytes. "Further, MAGEH1 overexpression inhibits proliferation, cell migration, and invasion in hepatocellular carcinoma, induces apoptosis in melanoma cell lines, and cell cycle arrest in multiple cancer cell lines." (PMID 33425727, 2020).
astrocytoma (2 papers, 2010 to 2020). "In REMBRANDT dataset, a clear association of MAGEH1 downregulation with poor OS was observed in astrocytoma (HR=2.75, 95% CI=1.69–4.46, p=0) and oligodendroglioma (HR=2.82, 95% CI= 1.3–6.1, p<0.01)." (PMID 33425727, 2020). "However, in TCGA dataset also, reduced MAGEH1 expression was associated with poor OS in astrocytoma (HR=6.72, 95% CI=3.78–11.93, p=0), oligodendroglioma (HR=7.75, 95% CI = 3.68–16.33, p=0) and mixed glioma (HR=7.29, 95% CI=2.63–20.21, p=0)." (PMID 33425727, 2020). "Furthermore, the analysis of histopathological data revealed a strong correlation of MAGEH1 downregulation with astrocytoma histology." (PMID 33425727, 2020).
glioma (2 papers, 2020 to 2022). A benign or malignant brain and spinal cord tumor that arises from glial cells (astrocytes, oligodendrocytes, ependymal cells). "Although the IDH mutation in glioma leads to a hypermethylation phenotype and global gene repression, interestingly, MAGEH1 exhibited higher expression in IDH mutant tumors." (PMID 33425727, 2020). "Using Kaplan-Meier analysis, we assessed the association of MAGEH1 expression with overall survival in glioma patients in the REMBRANDT and TCGA-LGG-GBM dataset." (PMID 33425727, 2020). "Further, we sought to analyze subgroup specific associations of MAGEH1 expression with overall survival in different histological subtypes of gliomas." (PMID 33425727, 2020). "Pan-glioma analysis revealed association of MAGEH1 with better survival in both, REMBRANDT (HR=2.92, 95% CI=2.3–3.71, p<0.001) and TCGA dataset (HR=5.76, 95% CI=4.39–7.55, p<0.001)." (PMID 33425727, 2020). "While both of these signaling pathways promote glioma progression, their functional association with MAGEH1 remains unclear." (PMID 33425727, 2020). "Low frequency mutations of MAGEH1 in glioma have been shown to affect its nuclear localization." (PMID 33425727, 2020). "Interestingly, the association of MAGEH1 with better survival of patients was separately validated in major histological and molecular subtypes of glioma." (PMID 33425727, 2020). "Treatment of GBM cell line U87MG and LN229 with DNA methyltransferase (DNMT) inhibitor 5-Azacytidine enhanced MAGEH1 mRNA expression thereby confirming the role of epigenetic regulation in MAGEH1 expression in glioma." (PMID 33425727, 2020). "In view of the reported overexpression of MAGED4 in glioma, we focused our further analysis on downregulated T2Ms using MAGEH1 as a representative member of this highly co-expressed T2M subgroup." (PMID 33425727, 2020). "In multivariate Cox regression analysis, MAGEH1 emerged as an independent prognosticator in lower grade glioma." (PMID 33425727, 2020). "In TCGA dataset, IDH mutant tumors, which are closely associated with the G-CIMP phenotype, exhibited higher MAGEH1 expression than non-IDH mutant gliomas (p<0.001)." (PMID 33425727, 2020). "Interestingly, analysis of both REMBRANDT and TCGA datasets brought out a steady decrease in MAGEH1 expression with advancing grades of glioma." (PMID 33425727, 2020). "REMBRANDT dataset revealed reduced MAGEH1 expression in glioma compared to its normal counterpart." (PMID 33425727, 2020). "This analysis revealed that some MAGEs including MAGED subfamily are overexpressed, while most others including MAGEE1, MAGEE2, MAGEL2, MAGEH1, NDN, and TRO are downregulated in glioma." (PMID 33425727, 2020). "Since the sample size for mixed glioma (oligoastrocytoma) in the REMBRANDT dataset was small (n=7), no conclusion on the association of MAGEH1 expression with survival could be drawn." (PMID 33425727, 2020).
hepatocellular carcinoma (2 papers, 2020 to 2022). A malignant tumor that arises from hepatocytes. "MAGEH1 expression has been reported to be downregulated in hepatocellular carcinoma and cholangiocarcinoma." (PMID 33425727, 2020).
liver cancer (1 paper, 2022). An epithelial or non-epithelial malignant neoplasm that arises from the liver. "Indeed, two of the examples we have highlighted, ARMCX2 and MAGEH1, have previously demonstrated promoter hypermethylation and gene silencing in ovarian and liver cancer, respectively." (PMID 35654826, 2022).
pancreatic cancer (1 paper, 2021). "These in silico results were validated using 43 pairs of resected pancreatic cancer samples, which also showed that the expression levels of MAGEH1, MAP3K3 and PODN were downregulated in tumor tissues." (PMID 33912458, 2021).
tumor (12 papers, 2018 to 2023). "Pathway analysis revealed that MAGEH1 correlated genes are involved in tumor immunity." (PMID 33425727, 2020). "In the univariate analysis for LGG, we used MAGEH1 expression, MAGED1 expression, age, gender, tumor histology, WHO grade, IDH mutation status, 1p/19q codeletion status, and MGMT promoter methylation status to analyze the association of these variables to patient outcome." (PMID 33425727, 2020). "In whole-tumor samples, overexpression of LAYN, MAGEH1, and CCR8, three of the most enriched genes in tumor-infiltrating Treg signature genes, was associated with a worse 5-year survival of CRC and NSCLC patients, pinpointing these genes as potential therapeutic targets." (PMID 29879107, 2018). "Among the 18 Treg-specific overlapping genes, ACP5, MAGEH1, TNFRSF9 and CCR8 were exclusively expressed in tumor-infiltrating Tregs and are potential immunotherapy targets for tumor-infiltrating Tregs." (PMID 35562760, 2022). "We found potential immunotherapy targets, for example, ACP5, MAGEH1, TNFRSF9 and CCR8 for tumor infiltrating Tregs and MT1 for exhausted CD8+ T cells (CD8+ Tex cells)." (PMID 35562760, 2022). "The C4 subset was annotated as Treg cells based on the high expression signature genes of tumor-infiltrating Tregs (FOXP3, IL2RA, IL2RB, IL2RG, IL10RA, MAGEH1, LAYN, and GATA3)." (PMID 34663810, 2021). "In this study, the impact of the tumor immune microenvironment (TIME) on specific gene expression (LAYN, MAGEH1, and CCR8) in tumor-infiltrating Tregs cells was confirmed, and these gene expressions were found to be correlated with immune therapy response, tumor-suppressive activity, and prognosis." (PMID 38077354, 2023). "Moreover, ACP5, MAGEH1, TNFRSF9 and CCR8 were especially populated in tumor-infiltrating Tregs and IKZF2 was only highly expressed in paratumor-infiltrating Tregs." (PMID 35562760, 2022). "Finally, MAGEH1, PODN, and MAP3K3 were identified as three mRNAsi-related tumor suppressor genes that were downregulated in tumor tissues and whose overexpression was associated with prolonged OS." (PMID 33912458, 2021). "We found that besides TNFRSF4, Treg functional signature genes such as FoxP3, CTLA4, TIGIT, TNFRSF18 (GIRT), CCR8, LAYN, and MAGEH1 were also overexpressed in C11-Tregs-FoxP3 of treatment-naive and non-MPR tumor lesions, but not for MPR tumor lesions." (PMID 35831283, 2022).
cancer (5 papers, 2010 to 2025). A tumor composed of atypical neoplastic, often pleomorphic cells that invade other tissues. "Two examples of CpG probes resistant to drug induced demethylation in the HCT116 parental cells (ARMCX2 and MAGEH1), showed the behavior expected for X-linked genes in non-cancer tissues." (PMID 35654826, 2022). "Further, genes negatively correlated to MAGEH1 expression were enriched in different immune associated pathways and cancer associated pathways including epithelial to mesenchymal transition and apoptosis." (PMID 33425727, 2020). "Unfortunately, little is known about the functional roles of ARMCX2 and MAGEH1 aside from their expression patterns in non-cancer human tissues." (PMID 35654826, 2022).
renal disorders (1 paper, 2021). "While there have not been many studies linking MAGEH1 to renal disorders, a few studies have provided evidence that MAGEH1 may play a critical role in the pathogenesis of renal diseases." (PMID 34788311, 2021).
MAGEH1 also shares sentences with these, for which no sentence is quoted: hookworm infection (3 papers); infection (2); Cerebral ischemia (1); cholangiocarcinoma (1); colorectal cancer (1); gastric cancer (1); glioblastoma (1); Hepatitis B (1); Insulin resistance (1); ischemia (1); mixed glioma (1); myeloma (1); oligoastrocytoma (1); oligodendroglioma (1); Sepsis (1); teratocarcinoma (1).